HLA-DQA1 (major histocompatibility complex, class II, DQ alpha 1)
Description:
Binds peptides derived from antigens that access the endocytic route of antigen presenting cells (APC) and presents them on the cell surface for recognition by the CD4 T-cells. The peptide binding cleft accommodates peptides of 10-30 residues. The peptides presented by MHC class II molecules are generated mostly by degradation of proteins that access the endocytic route, where they are processed by lysosomal proteases and other hydrolases. Exogenous antigens that have been endocytosed by the APC are thus readily available for presentation via MHC II molecules, and for this reason this antigen presentation pathway is usually referred to as exogenous. As membrane proteins on their way to degradation in lysosomes as part of their normal turn-over are also contained in the endosomal/lysosomal compartments, exogenous antigens must compete with those derived from endogenous components. Autophagy is also a source of endogenous peptides, autophagosomes constitutively fuse with MHC class II loading compartments. In addition to APCs, other cells of the gastrointestinal tract, such as epithelial cells, express MHC class II molecules and CD74 and act as APCs, which is an unusual trait of the GI tract. To produce a MHC class II molecule that presents an antigen, three MHC class II molecules (heterodimers of an alpha and a beta chain) associate with a CD74 trimer in the ER to form a heterononamer. Soon after the entry of this complex into the endosomal/lysosomal system where antigen processing occurs, CD74 undergoes a sequential degradation by various proteases, including CTSS and CTSL, leaving a small fragment termed CLIP (class-II-associated invariant chain peptide). The removal of CLIP is facilitated by HLA-DM via direct binding to the alpha-beta-CLIP complex so that CLIP is released. HLA-DM stabilizes MHC class II molecules until primary high affinity antigenic peptides are bound. The MHC II molecule bound to a peptide is then transported to the cell membrane surface. In B-cells, the interaction between HLA-DM and MHC class II molecules is regulated by HLA-DO. Primary dendritic cells (DCs) also to express HLA-DO. Lysosomal microenvironment has been implicated in the regulation of antigen loading into MHC II molecules, increased acidification produces increased proteolysis and efficient peptide loading.
Synonyms: CELIAC1; DQ-A1; DQA1; HLA-DQA; HLA-DQA1*
Tractability: Small molecule: a structure with a bound ligand is known. Antibody: its Gene Ontology location is reachable by antibodies, with high confidence; UniProt places it where antibodies can reach, with medium confidence; UniProt predicts a signal peptide or a membrane-spanning region. PROTAC: ubiquitination databases record sites on it.
Safety:
Unwanted effects reported when the protein is acted on. In parentheses: how it was acted on, where the effect was seen, and who reports it.
agranulocytosis (source: ClinPGx)
lapatinib-induced liver injury (source: ClinPGx)
pancreatitis (source: ClinPGx)
Gene: Protein-coding gene on chromosome 6 (32,628,179 to 32,647,062, forward strand). Ensembl gene ENSG00000196735.
Subcellular location: Cell membrane; Endoplasmic reticulum membrane; Golgi apparatus, trans-Golgi network membrane; Endosome membrane; Lysosome membrane
Pathways (Reactome):
Immune System: Co-inhibition by PD-1; Downstream TCR signaling; Generation of second messenger molecules; Interferon gamma signaling; MHC class II antigen presentation; Phosphorylation of CD3 and TCR zeta chains; Translocation of ZAP-70 to Immunological synapse
Gene Ontology:
Molecular function: protein binding; MHC class II protein complex binding; MHC class II receptor activity; peptide antigen binding
Biological process: antigen processing and presentation of exogenous peptide antigen via MHC class II; immune response; peptide antigen assembly with MHC class II protein complex; positive regulation of immune response; positive regulation of T cell activation; antigen processing and presentation
Cellular component: membrane; clathrin-coated endocytic vesicle membrane; endocytic vesicle membrane; ER to Golgi transport vesicle membrane; Golgi membrane; late endosome membrane; lumenal side of endoplasmic reticulum membrane; lysosomal membrane; MHC class II protein complex; plasma membrane; trans-Golgi network membrane; transport vesicle membrane; endoplasmic reticulum membrane; endosome membrane; Golgi apparatus
Genetic constraint (gnomAD): Loss-of-function variants: 6 observed, 2.74 expected, observed/expected ratio (o/e) 2.19. That is too few expected variants to judge how well the gene tolerates losing a copy. Missense variants: 65 observed, 64.04 expected, observed/expected ratio (o/e) 1.01, 90% interval 0.83 to 1.25. Synonymous variants: 24 observed, 20.8 expected, observed/expected ratio (o/e) 1.15, 90% interval 0.83 to 1.62.
Homologues: Orthologues: chimpanzee HLA-DQA1 (91% identical), tropical clawed frog mhc2-daa (45% identical), zebrafish mhc2daa (29% identical), zebrafish si:busm1-194e12.8 (27% identical), zebrafish mhc2d8.35a1 (25% identical), zebrafish mhc2d8.37a2 (25% identical), zebrafish mhc2dga (25% identical), zebrafish mhc2d8.46a (24% identical), zebrafish zgc:123107 (24% identical), zebrafish mhc2d8.37a1 (23% identical), zebrafish zmp:0000001006 (17% identical), zebrafish mhc2dca (15% identical). Paralogues in human: HLA-DQA2 (89% identical), HLA-DPA1 (56% identical), HLA-DOA (55% identical), HLA-DRA (53% identical), HLA-DMA (25% identical), HLA-DRB1 (23% identical), HLA-DQB2 (23% identical), HLA-DPB1 (22% identical), HLA-DQB1 (22% identical), HLA-DRB5 (22% identical), HLA-DMB (21% identical), HLA-DOB (21% identical), and 1 more.
Diseases named in the same sentence as HLA-DQA1 in open-access papers:
HLA-DQA1 is named in the same sentence as 193 diseases in open-access papers, as found by Europe PMC text mining. Sharing a sentence is not in itself a finding about the gene and the disease. The quoted sentences say what the papers report.
asthma (31 papers, 2014 to 2025). "Among the SNPs nominally associated with ANA+, rs9272346 (a SNP in the 5′ region upstream from HLA-DQA1) has been associated with the risk of asthma and type 1 diabetes." (PMID 40514052, 2025). "For example, HLA-DQA1*06:01 is the top signal associated with asthma in the Taiwanese cohort, which is consistent with a previous study of Chinese asthma families." (PMID 38702819, 2024). "HLA-DQA1 locus is among the MHC class II loci with the most polymorphisms linked to asthma and allergic disease." (PMID 36292755, 2022). "Fine-mapping the HLA region suggested that there are at least two asthma association signals in this region and that amino acid changes in HLA-DQA1, HLA-DQB1 and HLA-DRB1 genes are most likely to be the underlying causal variations." (PMID 35597955, 2022). "While previous asthma GWAS have implicated the classical and highly polymorphic HLA-DQA1 and HLA-DQB1 class II genes, our study revealed associations with HLA-DQA2 and HLA-DQB2 genes in risk for AOA." (PMID 35606880, 2022). "The association with asthma protection of HLA-DQA1*01:02 reached study-wise significance in the meta-analysis results from stage 1 and stage 2 (OR [95% CI] = 0.64 [0.50–0.82], p = 3.98 × 10–4)." (PMID 34880287, 2021). "Our results revealed that the classical HLA allele HLA-DQA1*01:02 was significantly associated with asthma protection." (PMID 34880287, 2021). "A two-stage association study targeting the genomic regions with an excess of African ancestry in the Canary Islands population revealed a novel classical HLA allele (HLA-DQA1*01:02) associated with asthma protection." (PMID 34880287, 2021). "There is considerable overlap between genes associated with asthma and other diseases with HLA-DQA1/B1 genes present in ~74% of significant terms." (PMID 35386986, 2021). "Fine-mapping of imputed HLA variation and putative CNVs demonstrated that there are likely to be at least two real, independent, association signals for asthma within the HLA region, one involving primarily HLA-DQA1 and HLA-DQB1 variation and one involving primarily HLA-DRB1 variation." (PMID 35597955, 2022). "Subsequent fine-mapping analyses of classical HLA alleles revealed a novel allele significantly associated with asthma protection (HLA-DQA1*01:02, meta-analysis p = 3.98 × 10–4, OR [95% CI] = 0.64 [0.50–0.82]) that had been linked to infectious and autoimmune diseases, and peanut allergy." (PMID 34880287, 2021). "Furthermore, the well-reported asthma-associated genes of HLA-DQA1, HLA-DRB1, and HLA-DRB5 have the most number of interacted edges with identified and predicted genes." (PMID 33066754, 2020). "Finally, the human orthologue of mouse H2-Aa, known as HLA-DQA1, encodes one of the HLA class II alpha chains and has been associated with autoimmune conditions including asthma, myasthenia gravis and celiac disease." (PMID 25153123, 2014). "Genetic polymorphisms of HLA-DQA1 and HLA-DQB1 have also been linked to asthma susceptibility in the northern Chinese population." (PMID 39766875, 2024). "At least two independent loci characterised by amino acid changes in the HLA-DQA1, HLA-DQB1 and HLA-DRB1 genes are likely to account for association of SNPs and CNVs in this region with asthma." (PMID 35597955, 2022). "Further studies will be needed to validate these results in other populations, as well as to assess the potential of HLA-DQA1*01:02 as an asthma biomarker." (PMID 34880287, 2021). "C1QB and HLA-DQA1 were overexpressed in the intestine, but were found to be reduced in asthma airways." (PMID 34332619, 2021). "Gene enrichment pathway and interaction analysis highlighted the dominance of the HLA-DQA1/A2/B1/B2 gene cluster across many immunological diseases including asthma, type I diabetes, and rheumatoid arthritis." (PMID 35386986, 2021). "In fact, a number of genetic variants from the MHC (some of them linked to HLA-DQA1 and HLA-DQB1) have been associated with asthma in large genetic association studies." (PMID 34880287, 2021).
asthma (continued). "For example, HLA-DRA, HLA-DOA, and HLA-DQA1 are all components of pathways that play a role in hypothyroidism, RA, asthma, and antigen processing and presentation." (PMID 32245788, 2020). "We identified eight eGenes whose eQTL colocalized with GWAS signals for pulmonary diseases, of which three, HLA-B, HLA-DQA1 and HLA-DQB1, had been previously associated with Asthma in GWAS and in the UK Biobank." (PMID 31746734, 2019). "Interestingly, certain HLA gene variants such as HLA-DQA1, HLA-DQB1, and HLA-DRB9 are also associated with asthma." (PMID 40661126, 2025). "Our preliminary results confirm that three asthma susceptibility loci: 2q12.1 (IL1RL1), 6p21.32 (HLA-DQA1/B1/A2/B2), and 22q12.3 (IL2RB) each have VDR- and IKZF3-binding sites either in enhancers predicted by GeneHancer to target these genes or within these genes themselves." (PMID 38567749, 2024). "For example, the HLA-DQA1*01:02:01 allele was associated with a 0.94-fold decrease in odds of asthma (95% CI: 0.92–0.95, p = 3.33 × 10−16), but HLA-DQA1*01:02:02 was not shown to be significantly associated (OR: 1.93, 95% CI: 0.99–1.06, p = 0.01)." (PMID 37923823, 2023). "Analyses in asthma have identified HLA-DQA1 as the likely driver gene." (PMID 35104449, 2022). "These analyses indicate that the most significant asthma locus in AOA is due to variation in two credible sets, whose effects are likely attributable to their impact on expression of the HLA-DQA2 and HLA-DQB2 genes and of the HLA-DQA1*03:01 allele." (PMID 35606880, 2022). "Moreover, a whole-genome sequencing association study of asthma severity in Europeans evidenced eight genome-wide significant loci previously reported as associated with asthma (IL1RL2, TSLP, HLA-DQA1, BACH2, C11orf30, RAD51B, and GSDMB) and lung function (THSD4)." (PMID 37761964, 2023). "A recent study reported colocalizations between eQTLs for HLA-B, HLA-DQB1, HLA-DQA1, HLA-DRA, TAP1, and RNF5 in induced pluripotent stem cells with asthma GWAS SNPs." (PMID 35606880, 2022). "Analysis of asthmatic GWAS showed differential inflammatory genes (e.g., HLA-DPB1, HLA-DQA1, FCER1A), which verified the inflammation levels of asthma model." (PMID 36439114, 2022). "This evidence agrees with human transcriptomic observations revealing a reduction of the HLA-DQA1 and HLA-DQB1 lung gene expression in patients with severe asthma compared to healthy controls." (PMID 34880287, 2021). "However, in the blood cell dataset analysis, HLA-DQA1 was decreased in asthmatics indicating a lack of gene expression is linked to risk and therefore inhibitory drugs at best would be ineffective and at worst intensify the asthma phenotype." (PMID 35386986, 2021). "Expression levels of HLA-DQA1/A2 (P = 0.0077), ORMDL3 (P = 0.0021), and RORA (P = 0.0005) were significantly lower in severe asthma subjects only compared to controls." (PMID 35386986, 2021). "The genes of HLA-DRB5, HLA-DQA1, HLA-DPB1, CTSW, PSMB9, and TAP2 have the most number of edges with both predicted genes and childhood-onset asthma-related genes." (PMID 32867763, 2020). "There were 8 of 11 genes (8/11 = 72.7%) showing significantly different expression profiles between severe asthma and controls; for example, GNGT2, TLR6, TTC19, LNPEP, SLC22A5 and HLA-DQA1." (PMID 33066754, 2020). "Moreover, the study pointed out two more genetic variants related to HLA-DQA1 rs9272131, previously indicted to be involved in allergies, together with variants in the TAP2 gene, located in close proximity to the HLA-DQA1 variant, also with previously reported connections with asthma and allergy." (PMID 30832275, 2019). "Finally, transcriptomic data from bronchial brushing and bronchoalveolar lavage (BAL) samples revealed that HLA-DQA1 (only available for bronchial brushing), HLA-DQB1, and HLA-DRB1 were downregulated in patients with severe asthma compared to healthy controls." (PMID 34880287, 2021).
celiac disease (31 papers, 2012 to 2026). An autoimmune genetic disorder with an unknown pattern of inheritance that primarily affects the digestive tract. "The HLA-DQA1 is widely recognized for its role in influencing the risk of various autoimmune diseases, including vitiligo, celiac disease, idiopathic membranous nephropathy, and multiple sclerosis." (PMID 38063198, 2023). "Specifically, expression levels of HLA-DQA1 were investigated in first instance due to the association with intestinal disorders (e.g., celiac disease) and drug response." (PMID 37153631, 2023). "HLA-DQA1 has been reported to be associated with immune-mediated diseases such as celiac disease and type 1 diabetes." (PMID 31382992, 2019). "Celiac disease is a common multifactorial disorder in which specific HLA-DQA1 and HLA-DQB1 alleles represent the major genetic predisposition." (PMID 23050549, 2012). "HLA-DQA1*05 carriage has been associated with various diseases, including celiac disease, type I diabetes, and protection against rheumatoid arthritis, suggesting that allelic variation in the HLA-DQA1 gene may contribute to aberrant adaptive immune responses." (PMID 39055374, 2024). "Diminished expression of BTNL2 may dysregulate ileal γδ IELs, with consequent intestinal inflammation, whilst overexpression of the celiac disease-associated HLA-DQA1*05 or other pro-inflammatory HLA alleles will further contribute to inflammation." (PMID 37407551, 2023). "The HLA-DQA1*05 allele is carried by 20%-40% of Europeans and has been strongly associated with autoimmune disorders, including celiac disease and inflammatory bowel diseases, whereas it has also been reported that the carriers tend to develop antibodies against infliximab." (PMID 36968684, 2023). "Furthermore, the low abundance of HLA-DQA1 highlights a fundamental question regarding its association with a wide range of human disorders such as celiac disease and the potential role of HLA-DQA1 protein levels change in disease processes." (PMID 33441579, 2021). "Different types of HLA complexes such as HLA-DQ2.5 (HLA-DQA1*05/HLA-DQB1*02), HLA-DQ8 (HLA-DQA1*03/HLA-DQB1*03:02), and HLADQ2.2 (HLA-DQA1*02:01/HLA-DQB1*02) are associated with coeliac disease pathogenesis and have been reported in more than 90% of coeliac disease patients." (PMID 32651763, 2020). "Finally, a variant in the HLA-DQA1 gene (rs2187668) was associated with increased risk for celiac disease and autoimmune diseases of the thyroid in both European American datasets." (PMID 32711518, 2020). "In addition, several studies have found a connection between HLA class II molecules and immune-mediated disorders, such as susceptibility loci in HLA-DRB1 for sarcoidosis and pemphigus and susceptibility loci in HLA-DQA1 for achalasia and celiac diseases." (PMID 31827636, 2019). "HLA-DQA1*01:03-DQB1*06:01 was found to be associated with wheat allergy, and patients who had celiac diseases carried HLA-DQA1*05:01-DQB1*02:01 and HLA-DQA1*03:01-DQB1*03:02." (PMID 37901344, 2023). "Since HLA-DQA1*05 relates to celiac disease (and Grave’s disease), it can be argued that some of the pathophysiological mechanisms are shared between celiac autoimmunity and the generation of ADA." (PMID 34946883, 2021). "For determination of the genetic risk of celiac disease, genes HLA-DQ8B1 and HLA-DQA1 were analyzed." (PMID 33260311, 2020). "The vast majority of celiac disease patients express human leukocyte antigen (HLA)-DQ2.5 (HLA-DQA1*05/HLA-DQB1*02, expressed by 90% of patients), and the remaining patients are either HLA-DQ8 (HLA-DQA1*03/HLA-DQB1*03:02) or HLA- DQ2.2 (HLA-DQA1*02:01/HLA-DQB1*02)." (PMID 34618841, 2021). "Pancolitis (E4) was found in only one of these children suggesting that the relationship between HLA-DQA1*05 and more severe colitis at diagnosis is not dependent on factors directly predisposing to celiac disease." (PMID 34946883, 2021).
celiac disease (continued). "The MHC is vital for the correct functioning of the immune system and therefore genetic variants in this region can have major health implications, for example HLA-DQA1 which was associated with SRH in our gene-based analysis, has previously been associated with coeliac disease." (PMID 27864402, 2017). "So far, only HLA-DQA1 and HLA-DQB1 loci have an application in the clinical practice of Celiac disease." (PMID 23050549, 2012). "Human leukocyte antigen (HLA) class II molecules on chromosome 6 are necessary factors for celiac disease where 90–95 % of all affected patients carry the HLA-DQA1*05:01-DQB1*02:01 haplotype and the remainder carry either the HLA-DQA1*03:01-DQB1*03:02 or HLA-DQA1*02:01-DQB1*02:02 haplotype." (PMID 26123480, 2015). "Alleles of the HLA-DQA1 and HLA-DQB1 genes are necessary for celiac disease but are not sufficient for disease development." (PMID 22615847, 2012). "Moreover, celiac disease (or Grave’s disease) is much less common in IBD patients than ADA development, so it can also be speculated that HLA-DQA1*05 facilitates the formation of ADA in a process dependent on IBD." (PMID 34946883, 2021). "The goal of this analysis was to test the hypothesis that the known HLA-DQA1 and HLA-DQB1 celiac disease high-risk alleles were not the only celiac disease alleles within the xMHC." (PMID 22615847, 2012). "The analyzes revealed that ClK cells expressed HLA-DQA1 molecule and identified a narcolepsy-cataplexy associated allele (namely, HLA-DQB1*0602), whereas no alleles associated with intestinal diseases (e.g., celiac disease, inflammatory bowel diseases) or co-morbidities were found (e.g., diabetes)." (PMID 37153631, 2023).